TYR (tyrosinase)
Diseases named in the same sentence as TYR in open-access papers (continued):
Sharing a sentence is not in itself a finding about the gene and the disease.
cancer (95 papers, 2002 to 2025). A tumor composed of atypical neoplastic, often pleomorphic cells that invade other tissues. "In melanoma therapy, the ability of compounds to inhibit tyrosinase activity is associated with the sensitivity of cancer cells to radiotherapy and chemotherapy, by reducing the production of cancer cells protecting melanin." (PMID 40869266, 2025). "Cancer-specific cf-mRNA alterations were first discovered in 1999 (Refs 7, 8), where cancer-associated viral RNA and tyrosinase mRNA were identified in the circulation of cancer patients." (PMID 38682644, 2024). "In addition to their use in cancer therapy, the ability to inhibit tyrosinase is also associated with the possibility of using carbazole derivatives in the food and materials industry." (PMID 40869266, 2025). "These may include cancers involving integrin trafficking, autoimmune conditions linked to Toll-like receptor signaling, and pigmentary diseases dependent on tyrosinase maturation." (PMID 40868968, 2025). "Moreover, certain terpenoids displaying inhibitory effects on tyrosinase offer opportunities for addressing skin pigmentary disorders and cancers linked to melanogenesis dysfunctions." (PMID 38474692, 2024). "Moreover, the rate of TYR somatic mutation was found to be significantly higher in AHM compared with PM or other cancers." (PMID 32966289, 2020). "We therefore try to see if intracellularly located nanocapsules containing tyrosinase can remove the intracellularly synthetized tyrosine to suppress the growth of these cancer cell lines." (PMID 40370596, 2025). "Quercetin is a prodrug that is converted into its active form, o-quinine, by cancer cells with high expression of tyrosinase." (PMID 40732270, 2025). "The examined activities included inhibition of tyrosinase, cytotoxicity against cancer cell lines, and antimicrobial effects against S. mutans." (PMID 39942603, 2025). "Further research should investigate the inconsistent effects of the tested compounds on enzymatic activity inhibition and their ability to inhibit the proliferation of cancer cells with low and high tyrosinase production in vitro." (PMID 41155937, 2025). "In our study, the strong antitumor activity of PolyHb–Tyr–nano in non-tyrosinase-expressing cancers was unexpected." (PMID 40867327, 2025). "The increased tyrosinase activity in these types of cancer leads to accumulation of melanin content, which protects cancer cells from chemo- and radiotherapy due to interaction with drugs and absorbing radiation." (PMID 39409408, 2024). "It exerted its action by targeting several signalling pathways according to the type of cancer, such as reducing the action of topoisomerase 1 and tyrosinase enzyme." (PMID 39478959, 2024). "After entering cancer cells, 134 was firstrapidly hydrolyzed by esterase to produce intermediate 1 (134a), which was further oxidized into intermediate 2 (134b) by tyrosinase." (PMID 38422393, 2024). "A recent prominent vaccine of interest is ECI-006, which is a combination mRNA cancer vaccine comprising TriMix (mRNA encoding DC activation molecules CD40L, CD70, and caTLR4) and mRNA encoding TAAs (tyrosinase, gp100, MAGE A3, MAGE C2, and PRAME)." (PMID 37744371, 2023). "In this study, the anti-cancer, anti-tyrosinase, and antioxidant activities of essential oils (EOs) of berries and leaves of Juniperus phoenicea grown wild in North of Tunisia were investigated." (PMID 38005268, 2023). "The results indicated that the pathways in the cancer signaling pathway (with 30 associated genes), PI3K/Akt signaling pathway (with 20 associated genes) and EGFR tyrosinase inhibition resistance (with 16 associated genes) were the main signaling pathways." (PMID 36768602, 2023). "The increase in tyrosinase activity in cancerous cells in some cancer types has drawn attention to the importance of the use of tyrosinase in the treatment of these types of cancer." (PMID 36558187, 2022).
cancer (continued). "Ethyl acetate and methanolic extracts also showed considerable in vitro biological activities, but petroleum ether extract revealed the highest potential against tyrosinase, ultraviolet radiations, and cancer cell proliferation." (PMID 36440354, 2022). "In our cohort, fourteen patients harbored a monoallelic P/LPV associated with recessive disorders (NTHL1, RECQL4, ERCC3, FANCA, and BLM) and one patient harbored PV in a low penetrance cancer gene (TYR)." (PMID 36132150, 2022). "Nevertheless, the activity of tyrosinase, a key enzyme for melanin biosynthesis, will influence cancer signaling because melanin production can contribute to diverse signaling pathways." (PMID 35204163, 2022). "TMD has been reported to have various functionalities such as anti-cancer, immune modulation, antioxidant, and anti-fibrinolytic activity, angiotensin-converting enzyme, and tyrosinase inhibitory activity." (PMID 34206411, 2021). "Our approach of using tyrosinase-expressing E. coli enables non-invasive, longitudinal monitoring of bacterial targeting and proliferation in cancer using multispectral optoacoustic tomography." (PMID 34952915, 2021). "Our results demonstrate that using tyrosinase-expressing E. coli enables non-invasive, longitudinal monitoring of bacterial targeting and proliferation in cancer using MSOT." (PMID 34952915, 2021). "Three nsSNPs; rs1126809 (TYR), rs10936600 (LRRC34), and rs757978 (FARP2), were found as the most damaging cancer pathogenic variants." (PMID 34373545, 2021). "Lakoochin A, a compound isolated from Artocarpus lakoocha and Artocarpus xanthocarpus, has an inhibitory function of tyrosinase activity and melanin production, but the anti-cancer effects are still unclear." (PMID 30200660, 2018). "Subsequently, stable tyrosinase-expressing cell lines were sorted by flow cytometry out of these infected cancer cell lines." (PMID 27283901, 2016). "Several systems expressing toxic or suicide genes driven by other cancer specific promoters such as hTERT, Tyrosinase, Survivin and Midkine were developed in the past decade." (PMID 24742710, 2014). "The melanin induced by TYR gene in cancer cells can thus be viewed as an attractive target for some of these promising agents." (PMID 23508226, 2013). "Due to its biocompatibility, biodegradability, anti-inflammatory, antibacterial, antioxidant, UV-protective, anti-tyrosinase, anti-aging, and anti-cancer properties, sericin is increasingly used in biomedical fields like drug delivery, tissue engineering, and serum-free cell culture media." (PMID 39590526, 2024). "Bandage-based biosensors are also well-performance wearable electrochemical sensors for monitoring wound healing and detecting the presence of tyrosinase (TYR) enzyme cancer biomarker in the presence of its immobilized catechol substrate for melanoma cancer screening and diagnosis." (PMID 39091290, 2024). "Several studies have reported a correlation between tyrosinase and cancer." (PMID 35204163, 2022). "Eight patients harbored monoallelic variants in high/moderate penetrance cancer genes associated with autosomal dominant inheritance and a second variant in a gene associated with a recessive disorder (MUTYH, FANCA, NTHL1) or low penetrance cancer (TYR)." (PMID 36132150, 2022). "Besides, this is the first research on the inhibitory activity (against cholinesterase and tyrosinase) and antiproliferative screening of this shrub and its main components in the specified group of cancer cell lines." (PMID 36552522, 2022). "In addition to HCA applications in cancer treatment, these compounds inhibit tyrosinase, the enzyme responsible for the enzymatic browning of fruits and vegetables." (PMID 34206859, 2021).
cancer (continued). "Biological efficiency was investigated by enzyme inhibitory assays (cholinesterases, tyrosinase, amylase, and glucosidase) and anti-cancer efficacy tests (anti-proliferative activities with the iCELLigence technology, colony formation and wound healing scratch assays)." (PMID 29864137, 2018). "Moreover, expression of the liver-specific (Ttr and Alb) and melanin-specific genes (tyrosinase and Trp-1), abundantly expressed in the parent adult cancer cells, decreased significantly in the hybrids." (PMID 27468690, 2016). "To proof the concept of using the meprin α tail for expression and solubilization of other membrane bound proteins, we also tested this strategy for the cancer related tyrosinase TRP-2 (UniProtKB P40126, TRP2_HUMAN, tyrosinase related protein 2, DOPAchrome tautomerase)." (PMID 27054568, 2016). "Both tyrosinase and OATP1B3/ICG reporter systems have been used to track cancer development in mouse models, but have yet to be applied to studying cancer immunotherapies." (PMID 34657195, 2022). "PTPRJ is a receptor protein tyrosinase, and PTPRJ-pep19.7 is capable of binding and activating PTPRJ to bring about anti-cancer effects." (PMID 36430160, 2022). "Tissue expression was confirmed to be significantly different in cancer vs. control samples for DNA2, MAOA, PARP1, TYR, and HDAC1 in the IST Online database and for PTK2B, MAOA, PARP1, and TYR in the GEPIA2 database." (PMID 34199192, 2021). "Additional target antigens were verified experimentally and included several cancer epitopes that are actively being pursued for cancer immunotherapy, namely WT1, MG50, Tyrosinase, gp100 and NY-ESO-1." (PMID 33836029, 2021). "Two days post primary stimulation, we re-stimulated the 1383i TCR+ T cells with the tyrosinase positive cancer line MEL624 in the presence or absence of Siglec-5 Fc protein." (PMID 35290663, 2022). "KEGG enrichment showed that pathways in cancer, PI3K-Akt signaling pathway, MAPK signaling pathway, etc., Were ranked at the top, suggesting that the B. rhynchopetera Fairmaire may exert antioxidant, anti-melanin, and anti-TYR through these pathways." (PMID 40909999, 2025). "As TYR, LRRC34, and FARP2 genes play important roles in numerous cellular processes such as cell proliferation, differentiation, growth, and cell survival; therefore, any impairment on the protein function could be involved in the development of cancer." (PMID 34373545, 2021). "We postulate that the observed SKMel-188 cells sensitization to CV induced by both of the tested tyrosinase inhibitors may be related to a mechanism involving metal ion catalyzed H2O2-mediated oxidative stress, as has been observed in radio-chemo-sensitization of cancer cells." (PMID 34072104, 2021). "Furthermore, although the MAGE-1, MAGE-3, Melan-A, gp100, tyrosinase, HER-2, and NY-ESO-1 are expressed in normal testicular, retinal, and/or brain tissues, no autoimmune responses have been elicited in the clinical trials or animal experiments of cancer vaccines." (PMID 25126583, 2014).
skin disorder (34 papers, 2016 to 2026). Any deviation from the normal structure or function of the skin or subcutaneous tissue that is manifested by a characteristic set of symptoms and signs. "Its efficacy is attributed to diverse pharmacological activities—including anti-inflammatory, antioxidant, antimicrobial, and tyrosinase-regulating effects—which underlie its therapeutic potential against a range of skin disorders." (PMID 41601979, 2026). "The study targeted six enzymes associated with skin disorders: elastase, hyaluronidase, tyrosinase, collagenase, cycloxygenase and xanthine oxidase." (PMID 40231173, 2025). "As a result, tyrosinase inhibition is a crucial strategy to control melanin synthesis; therefore, tyrosinase inhibitors have gained interest in therapies for skin disorders associated with abnormal pigmentation and dermo-cosmetic treatments." (PMID 38581040, 2024). "In conclusion, CAFB is a promising ingredient for treating skin disorders caused by the overproduction of melanin and its underlying mechanisms involving the modulation of tyrosinase, mainly mediated by the regulation of the cAMP cascade and MITF pathway." (PMID 37408224, 2023). "Several skin disorders are linked with defectuous melanogenesis, and hence the research for alternative tyrosinase inhibitors among natural sources is increasing." (PMID 36145758, 2022). "Overactive tyrosinase produces excess melanin, which is also linked to skin disorders." (PMID 34567157, 2021). "These metabolites exhibit anti-inflammatory, antioxidant, antibacterial properties, and tyrosinase-regulating effects, making T. terrestris L. a promising candidate for treating multiple skin disorders." (PMID 41601979, 2026). "Results indicate very potent antioxidant activity for BU and potent anti-tyrosinase activity for both chalcones, which is discussed in relation to bioactivity toward protection from skin disorders and food oxidative spoilage." (PMID 37760066, 2023). "Tyrosinase has been recognized as a significant target for the treatment of skin disorders related to irregular pigmentation." (PMID 35206019, 2022). "Specifically, the anti-tyrosinase effect of this extract was significantly higher when compared to the other extracts, thus suggesting applications in skin disorders characterized by an increased tyrosinase activity." (PMID 32823710, 2020). "Based on these results, BID3 seemed to be a potent tyrosinase inhibitor for the treatment of skin disorders such as hyperpigmentation." (PMID 31921392, 2019). "G. purpureum extract was the most active extract in terms of antioxidant capacity, whereas the G. album extract exhibited the strongest inhibitory effect against tyrosinase, an enzyme involved in several skin disorders." (PMID 30925810, 2019). "Tyrosinase is a rate-limiting, copper-containing enzyme that controls the production of melanin in the human body, which can lead to a variety of skin disorders when overproduced." (PMID 29891812, 2018). "Advanced in silico methodologies, such as docking, molecular dynamics simulations, and MM-GBSA rescoring, were implemented to evaluate the interaction profiles of these compounds with key skin disorder-related enzymes, including elastase, tyrosinase, hyaluronidase, and xanthine oxidase." (PMID 40231173, 2025). "Tyrosinase is a key enzyme in the synthesis of melanin and thus inhibiting tyrosinase may help to skin disorders and hyperpigmentation problems." (PMID 34829642, 2021). "Therefore, searching for tyrosinase inhibitors are highly recommended to fight against these skin disorders." (PMID 32570898, 2020). "As RSV loaded SLN showed a higher percentage of tyrosinase inhibitory activity than kojic acid, a well-known tyrosinase inhibitor, the authors concluded that this colloidal formulation could be useful in the topical treatment of several skin disorders." (PMID 31349656, 2019).
skin disorder (continued). "Therefore, it was concluded generally that these hybrid molecules might be pondered as creditable medicinal scaffolds for the treatment of tyrosinase related ailments, particularly skin disorders." (PMID 38774615, 2024). "Therefore, it was concluded generally that these bi-heterocyclic molecules might be deliberated as commendable medicinal scaffolds for treating tyrosinase related ailments, particularly skin disorders." (PMID 34567157, 2021). "Thus, inhibition of tyrosinase activity is of major concern since several skin disorders may be controlled." (PMID 32392806, 2020). "Since the key role of tyrosinase in melanin pathway, research of molecules that inhibit tyrosinase have become increasingly important for medicinal and cosmetic products that may be used as powerful skin-whitening agents for treating skin disorders." (PMID 27829416, 2016).
neurodegenerative disease (26 papers, 2018 to 2025). A disorder of the central nervous system characterized by gradual and progressive loss of neural tissue and neurologic function. "It was found that the methanol extract of P. fruticosa was able to efficiently reduce activities of enzymes linked to neurodegenerative disease including acetylcholinesterase, butyrylcholinesterase and tyrosinase." (PMID 35368464, 2022). "Additionally, it is noteworthy that the BB extract inhibited the enzymes MAO–A, MAO–B, and tyrosinase, all of which are associated with neurodegenerative diseases." (PMID 39456443, 2024). "In addition, it also appraised their potential antineurodegenerative properties on the basis of their ability to inhibit enzymes associated with neurodegenerative diseases: acetylcholinesterase (AChE), butyrylcholinesterase (BChE), and tyrosinase (TYR)." (PMID 36014295, 2022). "Tyrosinase is another enzyme which is linked to neurodegenerative diseases, such as PD." (PMID 33916370, 2021). "Furthermore, H. physodes extract inhibited tyrosinase activity, the enzyme linked to neurodegenerative diseases." (PMID 33916370, 2021). "Moreover, another enzyme-tyrosinase, oxidizing excess dopamine to produce dopamine quinones, highly reactive species which induce neural damage and cell death, was also linked to PD and other neurodegenerative diseases." (PMID 33916370, 2021). "The extracts were also evaluated for the inhibition of key‐enzymes involved in degenerative diseases namely cholinesterase and tyrosinase for CNS‐related pathologies and amylase for metabolic‐related diseases." (PMID 40171554, 2025). "The capacity to inhibit enzymes that play a role in the progression of neurodegenerative diseases, such as acetylcholinesterase (AChE), butyrylcholinesterase (BChE), and tyrosinase was also studied." (PMID 37891906, 2023). "The inhibitory ability of the phenylethanoid against several enzymes implied in neurodegenerative diseases (tyrosinase, MAO-A, and AChE) was analyzed in vitro." (PMID 33266151, 2020). "The in vitro neuroprotective potential was evaluated through the analysis of the effect of the phenylethanoid against several enzymes implied in neurodegenerative diseases: tyrosinase, MAO-A, and AChE." (PMID 33266151, 2020). "The activity of tyrosinase, another enzyme related to neurodegenerative diseases, was inhibited by the H. speciosa extract and flavonoids." (PMID 30050651, 2018). "Since tyrosinase is also involved in neurodegenerative disease mechanisms, these findings suggest that such oils may serve as effective dietary components for the elderly, pending confirmation by in vivo studies." (PMID 40563295, 2025). "Furthermore, these thyme species exhibit significant enzyme-inhibitory activities against acetylcholinesterase and tyrosinase, highlighting their potential therapeutic value for neurodegenerative diseases and pigmentation disorders." (PMID 39795376, 2025). "Thus, the inhibition of AChE, BChE, and TYR is considered an important strategy in the management of neurodegenerative diseases." (PMID 39202972, 2024). "Additionally, BMEPS shows anti-cholinesterase and anti-tyrosinase activities which are relevant to neurodegenerative diseases." (PMID 37452077, 2023). "Furthermore, we evaluated their potential health properties by studying their antioxidant and in vitro anti-inflammatory activities and in vitro inhibitory effects on three enzymes involved in neurodegenerative diseases (acetylcholinesterase, butyrylcholinesterase, and tyrosinase)." (PMID 38671929, 2024).